HIF1A (hypoxia inducible factor 1 subunit alpha)
Diseases named in the same sentence as HIF1A in open-access papers (continued):
Sharing a sentence is not in itself a finding about the gene and the disease.
tumor (continued). "In GBM, tumour acidosis contributes to the acquisition of stem cell characteristics in non-stem cell tumours, fostering an invasive phenotype characterised by increased expression of HIF-1α and HIF-2α." (PMID 37686652, 2023). "In such cases, MYC and HIF1α may cooperatively tailor a gene expression program that takes advantage of the pro-tumorigenic aspect of each protein to fuel tumor growth." (PMID 37601651, 2023). "XIST levels in serum may be used as a tumor marker for TC promoted by HIF-1a, which could be treated by artemisinin." (PMID 37036874, 2023). "Interestingly, EVO inhibited glycolysis in tumor cells, which is suggested to be due to the elimination of HIF-1α-positive cells." (PMID 38067241, 2023). "Moreover, HIF-1α stabilization promotes the shift of tumor metabolism towards aerobic glycolysis to adapt to hypoxic conditions, leading to the accumulation of dicarbonyls and other AGEs." (PMID 38067186, 2023). "Finally, the mTORC1-mediated signaling pathway stimulates the synthesis of HIF-1α in hypoxic tumor cells." (PMID 37227584, 2023). "In this study, we demonstrated that the tumor inflammatory microenvironment leads to the abnormal activation of the Stat/HIF-1α/BNIP3 signaling pathway in skeletal muscle cells, which induces excessive mitophagy in skeletal muscle and ultimately leads to fatigue." (PMID 36814560, 2023). "Overexpression of HIF-1α can induce abnormal expression of the E-cadherin gene in the oxygen-deprived areas of tumor cells, which leads to the abnormal regulation of the related signaling pathway and affects intercellular adhesion, invasion, metastasis, and survival." (PMID 37681973, 2023). "Interestingly, in the present study, we observed that the triple-drug combination (TME) significantly attenuated the gene expression levels of Nrf2 and HIF-1α, thereby deactivating the antioxidant defence mechanism in tumor cells (p < 0.0001)." (PMID 37025487, 2023). "Different types of tumor hypoxia (continuous vs. intermittent) may have varying effects on HIF-1α and HIF-2α." (PMID 37520562, 2023). "In addition, HIF1A was positively related to tumor-suppressive immunity but was negatively correlated with anti-tumor immunity." (PMID 36994412, 2023). "We also show that myeloid HIF1α or HIF2α deletion abolishes the thrombosis-induced increases in pulmonary tumor formation and that myeloid HIF-dependent increases in tumor burden following pulmonary occlusion are associated with increases in tumor proliferation and vascularisation." (PMID 36291563, 2022). "The structures of nanocarriers capable of improve the transport of chemotherapeutic agents, as well as release O2 selectively in cancer cells, have decreased the hypoxic state with a downregulation of HIF-1α expression, resulting in a reduction in tumor growth and metastasis." (PMID 35681719, 2022). "Under hypoxic conditions, HIF-1α upregulates MDSCs derived exosomal miR-210, which not only enhances the function of MDSCs by increasing Arg-1 activity and producing NO, but also regulates endothelial cell activation to induce tumor angiogenesis." (PMID 36237333, 2022). "In addition, we also analyzed tumor angiogenesis genes, and the results showed that seven tumor angiogenesis genes (HIF1A, PDGFB, NRP1, VEGFB, FGFR1, ROBO1, and SLIT1) had substantially higher expression in the high-risk group compared with the low-risk group." (PMID 35311113, 2022). "For example, in glutamine-addicted clear cell renal cell carcinomas, the competitive consumption of glutamine by tumor cells results in local deprivation of extracellular glutamine, which activates HIF-1α and induces tumor-infiltrating macrophages to secrete IL-23." (PMID 35897036, 2022). "Similarly, the expression of CD47 protein on the surface of tumor cells is also affected by HIF-1α, and hinder the phagocytic ability of phagocytes to tumor cells through phosphorylation of signal regulatory proteins on the surface of macrophages α (SIRP α)." (PMID 36212414, 2022).
tumor (continued). "Another neoplastic condition in which hypoxia appears to support tumor stemness and drug resistance is non-small-cell lung carcinoma, in which the hypoxic state contributes to confer cisplatin resistance by overexpressing Tie1 in a HIF-1α-dependent way." (PMID 35870078, 2022). "Induction of PIAS4 by hypoxia also causes it to interact with and suppress the tumor suppressor VHL, facilitating its oligomerization, which inhibits its function as a tumor suppressor in HIF1α-dependent and independent manners, contributing to overall tumor progression." (PMID 35887358, 2022). "Notably, the response to radiotherapy was more powerful in HIF‐1α and/or Glut‐1 knockout tumours than in tumours treated with wortmannin only, particularly in tumours with double knockout." (PMID 35415942, 2022). "In addition, Zeb1 exerts its biological effects to induce glycolytic activity in response to hypoxia via the PI3K/Akt/HIF-1α signaling axis, which contributes to fostering an immunosuppressive tumor microenvironment (TME)." (PMID 35246504, 2022). "Additionally, a number of studies have examined the link between HIF-1α and tumour response/regression and the occurrence of pCR following nCRT." (PMID 36032656, 2022). "In an antitumor test in mice, AC1-004 significantly reduced the tumor size by about 58.6% without adverse reactions such as weight loss, and is expected to become a new structural type of HIF-1α inhibitor." (PMID 35684364, 2022). "Moreover, the interaction between AGE/RAGE and Ras is reported to induce the activation of HIF1α and enhance tumor aggressiveness." (PMID 35701529, 2022). "In addition, it has been shown that TACE increases tumor hypoxia and the expression of hypoxia-inducible factor 1α (HIF-1α)." (PMID 35158918, 2022). "However, subsequent validation is still required for MGMT and HIF-1α due to the weak expression in all tumor lesions." (PMID 36591483, 2022). "ELR510444, a small molecule blocking HIF and known as a microtubule blocker, inhibited tumor angiogenesis in mice model of renal cell carcinoma, which was contributed to the suppression of HIF-1α and HIF-1β activity (0-100 nM) and the induction of microtubule destabilization (EC50, 27 nM)." (PMID 35784750, 2022). "Notably, multiple studies have demonstrated that the hypoxia-induced expression of HIF1α in tumor cells directly upregulates the expression of programmed death-ligand 2 (PD-L1 and PD-L2) on tumor cells." (PMID 35203357, 2022). "On the other hand, adenosine was observed to increase HIF1α protein accumulation under hypoxia situations through cell surface A3R interaction in various tumors, and HIF1α plays an important role in tumor VEGF expression and angiogenesis." (PMID 35721189, 2022). "Further, there is evidence that tumor cells may constitutively express HIF-1α even under normoxic conditions, suggesting that tumor cells may be capable of decoupling HIF-1α regulation from local oxygen tension." (PMID 36818371, 2022). "VHL-/- ccRCC tumours and cell lines produce both HIF-1α and HIF-2α or HIF-2α alone." (PMID 36551652, 2022). "In addition, inhibition of HIF-1α expression reduced the motility and chemosensitivity of tumor cells due to the negative regulation of miR-224-3p expression." (PMID 36157351, 2022). "This study aimed to elucidate whether NBO2 water could act as a radiosensitizer via regulation of HIF-1α in a tumor-bearing mouse model." (PMID 35743281, 2022). "After irradiation, HeLa and C33A cells overexpressing HOTAIR increased HIF-1α expression, leading to radioresistance and promoting tumor growth, but this effect could be neutralized by miR-217 mimics." (PMID 35692795, 2022). "The results of PA imaging and HIF-1α protein expression analysis demonstrated that this system could efficiently deliver O2 and alleviate tumor hypoxia." (PMID 36145513, 2022). "HIF-1α is not only expressed in tumor cells but also in some immune cells and may affect the infiltration and function of immune cells." (PMID 36685566, 2022).
tumor (continued). "Additionally, HIF-1α staining confirmed that HMP-based treatment indeed alleviated the tumor hypoxic state." (PMID 35595770, 2022). "The ROS productions don’t only destroys tumor tissues but also decreases the HIF-1α expression." (PMID 35616278, 2022). "We investigated whether the radiosensitivity induced by Glut‐1/HIF‐1α knockout was related to tumour death." (PMID 35415942, 2022). "Moreover, the stabilization of the transcription factor, hypoxia-inducible factor-1α (HIF-1α), in the tumor core upregulates several pro-angiogenic genes expressing cytokines and growth factors that subsequently induce an angiogenic response." (PMID 35511379, 2022). "HIF-1α provides energy to tumor cells, thereby enhancing tumor cell viability." (PMID 36226248, 2022). "Additionally, HIF-1α enhances the gene expression of several enzymes to improve glucose consumption and energy metabolism in tumor cells, known as aerobic glycolysis or the Warburg effect." (PMID 35527284, 2022). "As the tumor mass grows larger, tissue hypoxia can set in, resulting in high HIF-1a activation, which may be relieved as the tumor disseminates, possibly due to correlated vascularization, or access to oxygen in smaller disseminated nodes." (PMID 35565326, 2022). "Positivity for HIF-1α in the tumor tissues of patients corresponded to lower OS." (PMID 35205682, 2022). "However, in cancer cells, HIF-1α degradation is prevented, leading to cancer cell metabolic switch and tumor progression." (PMID 35202089, 2022). "Thus, results from previous studies and our study strongly suggest that HIF1A poses a great potential to control the tumor progression in BPH." (PMID 36059933, 2022). "In addition to regulating cellular metabolism, HIF-1α plays a key role in mediating tumour proliferation and angiogenesis." (PMID 36076967, 2022). "Tumor hypoxia can increase the expression of HIF-1α, VEGF and other angiogenic factors." (PMID 35903690, 2022). "Although we found that HITT regulated glycolysis under normoxia independently of HIF-1α, HITT-inhibited tumor growth in vivo may be at least partially attributed to the activation of HIF-1α in xenografts." (PMID 35909936, 2022). "Furthermore, antiangiogenic drugs help inhibit tumor growth and metastasis via the HIF-1α signaling pathway." (PMID 35769999, 2022). "Furthermore, the lactate levels in the plasma of cancer patients were positively correlated with the HIF-1α and Rab27a proteins in tumor tissues." (PMID 36531060, 2022). "STAT3 and HIF-1α are known to interfere with tumor suppression and increase tumor angiogenesis." (PMID 35482149, 2022). "Overall, a high expression of HIF-1α may play a role in promoting tumor growth, but in the pediatric population, it is negatively correlated with severe clinical features." (PMID 36091021, 2022). "Furthermore, UBE2S was demonstrated to be negatively correlated with the von Hippel-Lindau tumor-suppressor (pVHL), which mediated the ubiquitin-dependent proteolysis of HIF1A, in multiple tumor cell lines." (PMID 36138435, 2022). "HIF-1α plays a crucial role in key stages of metastatic dissemination, including angiogenesis, epithelial-mesenchymal transition, invasion, cancer stem cell maintenance, tumour cell dormancy, extracellular vesicle release, and pre-metastatic niche generation." (PMID 35801079, 2022). "Moreover, tumor B cells have increased the production of EVs through HIF-1α, enhancing Rab27a transcription in tumor B cells." (PMID 35563739, 2022). "After 3 weeks of injecting, TAK-242 (TLR4 inhibitor, 20 μg/mouse), PDTC (NF-κB inhibitor, 60 μg/mouse), or YC-1 (HIF-1α inhibitor, 20 μg/mouse) were injected into the subcutaneous tumor basement, and, after an hour, LPS (5 μg/mouse) was injected by the same method." (PMID 35464826, 2022).
tumor (continued). "Consistent with this hypothesis, it has been shown that the expression of several proangiogenic factors, such as VEGF, MMP2, MMP9 and HIF-1α, which are highly upregulated in IHs during the proliferative phase, decrease after tumor involution." (PMID 35563552, 2022). "A combination of HIF-1α inhibitors with immunotherapy with checkpoint blocking antibodies may represent a novel approach to boost anti-tumor immunity and enhance the efficacy of SABR." (PMID 35805044, 2022). "However, the exact role of HIF-1α in tumor lipid metabolism is not well understood at this time and is likely cancer type specific." (PMID 36140753, 2022). "High expression of HIF-1α protein was indicated in most tumor tissues and their metastatic sites." (PMID 35222641, 2022). "They demonstrated that exosomal miR-549a could reduce the expression level of hypoxia-inducible factor 1 alpha subunit (HIF1α) by binding to the 3’-UTR region of HIF1α mRNA, which in turn attenuate tumor angiogenesis and endothelial cell migration in ccRCC." (PMID 36620603, 2022). "It is suggested that the regulation of HIF-1α may be a new approach to overcome the drug resistance of tumor cells." (PMID 35800058, 2022). "Thus, m.3571insC reduced the tumourigenic potential of the osteosarcoma cells, while allotopic expression of wild‐type ND1 rebalanced the α‐KG/SA ratio, restored HIF‐1α stability and sustained tumour growth." (PMID 35842901, 2022). "In addition to being a glycolytic rate-limiting enzyme, PKM2 enters the nucleus to maintain HIF-1α stability, while inducing macrophage polarization, which diminishes the anti-tumor activity of macrophages." (PMID 36588722, 2022). "In addition, in vivo models showed that overexpression of miR-138-5p markedly slowed down tumor growth, decreasing both hypoxia-inducible factor 1-alpha (HIF-1α) and SIRT1 expression levels and, consequently, autophagy." (PMID 36558998, 2022). "Thus, by potently inhibiting HIF-2α and partially inhibiting HIF-1α, these compounds can be expected to exert maximal anti-tumor activity while maintaining a therapeutic window for minimal toxicity to normal tissue." (PMID 36097192, 2022). "RT exacerbates the hypoxic stress by inducing upregulation of hypoxia-inducible factor-1α (HIF-1α), a key transcription factor of hypoxia that is known to potentiate the immunosuppressive functions of Tregs and thus protects tumor cells from immune attack in the hypoxic environment." (PMID 35681654, 2022). "Additionally, the topoisomerase inhibitor Topotecan attenuates tumor growth and angiogenesis through the inhibition of HIF-1α and its target genes expression in GBM in vivo models." (PMID 35409080, 2022). "In addition, HIF-1α is a vital transcription factor that functions in tumor survival, proliferation, metabolism, invasion, metastasis, and angiogenesis." (PMID 35236823, 2022). "Previous studies have shown that tumors under a hypoxic environment can induce an important hypoxia-responsive element, hypoxia-induced factor-1α (HIF-1α), which can increase tumor migration, invasion, and metastatic ability by promoting epithelial-to-mesenchymal transition (EMT) in tumor cells." (PMID 36139386, 2022). "HIF1A is a transcription factor that is required for a tumor to adapt to hypoxia." (PMID 35774500, 2022). "In addition, tumor hypoxia induced an HIF-1α/IL-1β signaling loop between cancer cells and TAMs that leads to EMT in HCC." (PMID 36679900, 2022). "Red propolis produces antioxidant effects, also inhibits angiogenesis through the modulation of angiogenic factors and inflammation, and reduces the levels of VEGF and HIF-1α, and this shows the relationship between angiogenesis, oxidative stress, and tumor hypoxia." (PMID 35754701, 2022). "Even if tumor cells metabolize glucose through the “Warburg effect”, the accumulation of its product lactate salts will further induce hypoxia, which in turn will further promote lactate production, and HIF-1α is an important regulator of this process." (PMID 36686771, 2022).
tumor (continued). "HIF-1α is a potent stimulant for angiogenesis necessary for tumor growth and progression." (PMID 36818371, 2022). "Moreover, HIF-1α can enhance glycolytic activity by regulating several glycolytic enzymes in tumor cells." (PMID 36140753, 2022). "Furthermore, HIF-1α increases resistance against apoptosis in tumor cells by inhibition of Bid and Bax, which are pro-apoptotic proteins of the Bcl-2 family, as well as by enhancing the expression of apoptosis inhibitors." (PMID 36140753, 2022). "Sensing hypoxia by HIF-1α impairs the apoptotic potential of tumor cells, thus increasing their proliferative capacity and contributing to the development of a chaotic vasculature in the tumor microenvironment." (PMID 35795658, 2022). "Collectively, HIF-1α participates in the regulation of multiple radioprotective mechanisms in hypoxic tumors and, thus, the inhibition of the HIF-1α involved pathways may be targeted for radiosensitization of tumor cells." (PMID 35328212, 2022). "Hypoxia and HIF-1α activation are also known to promote tumor progression and metastasis." (PMID 36669005, 2022). "Tumor sections showed increased apoptosis and a decrease in Ki-67 and HIF-1α." (PMID 36077845, 2022). "In addition, LOX secreted by CAFs can promote tumor proliferation by enhancing the Warburg effect mediated by the AKT/p70S6K/HIF1-α pathway in tumor cells." (PMID 36293126, 2022). "In conclusion, this is considered uncovered that upregulation of WTAP expression by HIF-1α intercedes with miRNA processing, accelerates the Warburg impact, and advances the event and advancement of tumor, thus giving a novel viewpoint on m6A adjustment in OC movement." (PMID 35733918, 2022). "suggests that inhibition of HIF-1α would unleash the activity of tumor-infiltrating NK cells." (PMID 36439512, 2022). "The inhibition of HIF-1α by EZN-2968 reduced tumor growth by inhibiting cell proliferation through a delayed progression of the S-phase, which might be caused by the shift to a mitochondrial oxidative metabolism." (PMID 36551540, 2022). "Recent studies have outlined the ability of ROS to engage with CAFs in a two-way cross-talk, where CAFs increase the levels of ROS observed in the tumor tissue, promoting cancer growth and invasiveness, while ROS activate the CAFs through the upregulation of HIF1α." (PMID 35163777, 2022). "The mutations in tumor suppressor genes PTEN and pVHL are associated with the upregulation of HIF-1α which may contribute to poor prognosis in PTEN or pVHL-deficient cancers." (PMID 35681691, 2022). "Silencing Notch1 signaling or HIF-1α inhibition showed a notable anti-growth effect in early treatment with doxycycline or chetomin, indicating that HIF-1α might be a promising therapeutic target even in an early stage of tumor progression." (PMID 36183290, 2022). "Results from analysis of tumor images and animal weights further confirmed that GSK3α promoting tumor growth could be inhibited by silencing of HIF1α." (PMID 35292059, 2022). "However, increased HIF-1α and HIF-2α protein levels in diagnostic tumor biopsies have been correlated with poor prognosis in a variety of cancer types." (PMID 35629169, 2022). "Furthermore, in HER2-positive and in triple-negative breast cancer, tumor cell proliferation and survival in the hypoxic tumor environment were associated with REDD1 down-regulation and HIF-1α stabilization." (PMID 36077083, 2022). "HIF-1α increases vascular endothelial growth factor (VEGF) to enhance intra-tumor angiogenesis." (PMID 35527284, 2022). "HIF-1α is ubiquitously expressed and overexpressed by tumor cells." (PMID 35267480, 2022). "Moreover, the results confirmed that the expression of HIF-1α was significantly higher in the tumor tissue in comparison with the small intestine (P < 0.05)." (PMID 35346234, 2022).